EGFR (epidermal growth factor receptor)
Diseases named in the same sentence as EGFR in open-access papers (continued):
Sharing a sentence is not in itself a finding about the gene and the disease.
tumor (continued). "Tumor antigens that have been successfully targeted include epidermal growth factor receptor (EGFR), ERBB2, vascular endothelial growth factor (VEGF), cytotoxic T lymphocyte-associated antigen 4 (CTLA4), CD20, CD30 and CD52." (PMID 41294857, 2025). "By binding to EGFR, cetuximab inhibits ligand-induced receptor signaling, which helps modulate tumor cell growth." (PMID 40149618, 2025). "In contrast, the tumor growth from shControl wild‐type and mutant EGFR overexpressing cells supported by stiff VitroGel were significantly reduced upon agrin silencing." (PMID 40165020, 2025). "The activity of EGFR-mediated kinases is critical to promote greater malignancy, making it a promising target to prevent tumor progression." (PMID 40191718, 2025). "This design enables selective binding to EGFR-expressing tumor cells, internalization, and intracellular release of the cytotoxic agent, resulting in mitotic arrest and cell death." (PMID 41375018, 2025). "The most important predictors captured tumor heterogeneity and microstructural uniformity, highlighting the biological relevance of radiomic patterns in EGFR-positive tumors." (PMID 41179692, 2025). "NE similarly promotes tumor cell apoptosis via death receptor cleavage, yet also enhances tumor growth through EGFR signaling and angiogenesis." (PMID 40805288, 2025). "Our results showed that ectopic expression of Myc-CaM elevated EGFR protein levels and promoted H1975 xenograft tumor growth." (PMID 40447190, 2025). "For instance, in epithelial ovarian cancer, a positive correlation has been detected between EpCAM and EGFR expression in tumor tissues." (PMID 40699639, 2025). "Our longitudinal pharmacogenomic analysis successfully identified subclones in EGFR–TKI-induced tumor progression and suggested therapeutic candidates for each subclone." (PMID 40615564, 2025). "Trajectory analysis revealed that C2_STAT1+ cells were derived from the C1_EGFR+ cell population, marking a transcriptional shift of tumor cells toward a highly immunosuppressive and multidrug-resistant tumor phenotype." (PMID 40948762, 2025). "Altered NOTCH signaling further promotes crosstalk with the KRAS and EGFR signaling pathways, amplifying tumor proliferation and invasion while remodeling the tumor microenvironment to favor immune evasion and angiogenesis." (PMID 41451346, 2025). "Key classes of compounds like alkaloids, flavonoids, terpenes, and polyphenols have shown anti-tumor effects through modulation of apoptosis, cell cycle arrest, and inhibition of oncogenic pathways such as NF-κB, EGFR, and COX-2." (PMID 41149466, 2025). "In vivo efficacy was evaluated in NSCLC xenograft models, with subsequent tumor resection for ex vivo quantification of EGFR and cMET levels." (PMID 40452841, 2025). "Tumor cells from the tumor cell line PC9 (HLA-A2+ EGFR mutant NSCLC) were either cocultured with PBMCs in their native state or after stimulation with IFN-γ and TNF-α to increase antigen presentation." (PMID 40459946, 2025). "CD73SC expression was detected in 18% of cases, predominantly in early-stage (p = 0.037), PD-L1-negative (p = 0.030), and non-EGFR-amplified (p = 0.0018) tumours." (PMID 40149368, 2025). "The epidermal growth factor receptor (EGFR) pathway is frequently activated in OSCC and is associated with aggressive tumor behavior and poor prognosis." (PMID 40427514, 2025). "Examples of TPPs that were developed to specifically target EGFR were previously reported; these species were shown to facilitate enhanced tumor selectivity and intratumoral delivery of therapeutic agents in EGFR-overexpressing malignancies." (PMID 40942060, 2025). "Preclinical studies have shown that an overactive VEGF/VEGFR pathway and tumor angiogenesis play a crucial role in the development of resistance to EGFR-TKIs." (PMID 40277759, 2025). "A significant positive correlation between STARD4 and EGFR mRNA expression was found in tumor tissue samples obtained from HCC patients." (PMID 40831538, 2025).
tumor (continued). "EGFR nuclear translocation has been reported in several types of cancer, and nuclear EGFR signaling is involved in DNA repair, tumor progression, and cell proliferation." (PMID 39940647, 2025). "In NSCLC, DTP cells mediate resistance to EGFR-targeted therapies such as osimertinib, resulting in tumor recurrence despite initial effective responses." (PMID 40894234, 2025). "At this time point, the fluorescence signal of Pan‐IR700 visually matched well to the immunofluorescent signal of EGFR showing the A431 tumor cell membrane." (PMID 40830817, 2025). "In EGFR‐positive cases (A, B, and C), most of the tumor regions are highlighted in red and these often correspond to areas showing dense tumor growth, nuclear atypia, or solid patterns, common features that are observed in EGFR‐mutant adenocarcinomas." (PMID 40965349, 2025). "GOLPH3 affected EGFR recycling and post-translational modifications and promoted tumour growth by triggering autophagy." (PMID 40293576, 2025). "Sustained EGFR activation activates downstream signaling networks and contributes to tumor cell growth, survival, and motility." (PMID 40940319, 2025). "The anti-VEGF effect driven by EGFR/cMET targeting exhibited stronger and more promising anti-tumor results." (PMID 40452841, 2025). "Further, Univariate Cox analysis revealed that age, EGFR mutation type, Brain radiotherapy, TKI treatment response prior to TRT initiation, BED of TRT, and tumor status at the time of TRT initiation were significantly related to OS." (PMID 41383503, 2025). "This amplification functions as a parallel signaling route that effectively bypasses the blockade of EGFR, sustaining tumor growth despite anti-EGFR therapy." (PMID 40940901, 2025). "Of note, the RD state represents a residual lesion that cannot be eradicated after EGFR‐TKIs treatment, and the PD state indicates a de novo resistance of a tumour." (PMID 40162549, 2025). "In vitro, ALX148 enhanced the antibody-dependent cellular phagocytosis activity of the anti-EGFR antibody cetuximab in tumor cell lines." (PMID 41171165, 2025). "This interaction is driven by a CSF-1/EGF paracrine loop, wherein tumor cells secrete CSF-1 (which attracts CSF-1R-expressing macrophages), while macrophages in turn secrete EGF (which attracts EGFR-expressing tumor cells)." (PMID 40646332, 2025). "This potential arises from its ability to selectively infect cells that overexpress the Epidermal Growth Factor Receptor (EGFR), a receptor commonly found in high amounts on tumor cells." (PMID 41313526, 2025). "Small-molecule inhibitors aimed at the epidermal growth factor receptor (EGFR) have been documented to potentially impact the proliferation and differentiation of muscle cells, in addition to inhibiting tumor cell growth." (PMID 40242775, 2025). "This dual-targeted therapy effectively breaks the mechanism by which tumor cells escape drug inhibition through the EGFR/Akt pathway." (PMID 40125551, 2025). "MiR-218-5p can act as a tumour suppressor, inhibiting cell proliferation, migration, colony formation, tube formation, tumour growth, and angiogenesis by directly targeting EGFR via its 30-untranslated region (UTR)." (PMID 41226797, 2025). "High EGFR expression is observed in 50–70% of ESCC patients and is associated with tumor invasiveness and patients’ poor survival." (PMID 40722671, 2025). "By secreting a range of cytokines and chemokines, TAMs activate bypass pathways that promote tumor cell survival and proliferation, ultimately contributing to EGFR-TKI resistance." (PMID 40003951, 2025). "Our results revealed a significant upregulation of ADM expression in tumor tissues after resistance to EGFR-TKI treatment." (PMID 40529377, 2025).
tumor (continued). "A tumor targeting system was developed by presenting an epidermal growth factor receptor (EGFR)-targeting peptide (ETP) on the surface of PHA NPs, via PhaP mediated adsorption." (PMID 40555915, 2025). "Multivariate logistic regression analysis revealed maximum nodule diameter, consolidation-to-tumor ratio (CTR), mean CT values, presence of air bronchogram signs, and vascular convergence signs as independent predictors of EGFR mutations." (PMID 41357203, 2025). "The immunosuppressive effects of ANXA1 in CRC are also supported by its interaction with EGFR, a major signaling molecule involved in tumor development and therapeutic resistance." (PMID 41283264, 2025). "Research has demonstrated that silencing the expression of podoplanin in CAFs can effectively eliminate the resistance of tumor cells to EGFR-TKIs." (PMID 40003951, 2025). "A notable decrease in infiltrating CD8+ tumor‐infiltrating lymphocytes is observed in EGFR mutant LUAD, indicating potential factors hindering effector T‐cell induction and proliferation within the TME." (PMID 40130724, 2025). "This section aggregates evidence that EMT-coupled miR-200 suppression shapes both primary and acquired resistance to EGFR-TKIs and wires immune evasion through PD-L1 and the tumour microenvironment." (PMID 41300764, 2025). "More importantly, we found that knockdown of SYVN1 resulted in a faster attenuation of EGFR signaling activity, which is detrimental to the rapid proliferation of tumor cells." (PMID 40877231, 2025). "For instance, EVs’ release results in increased tumor invasiveness by transferring tumor promoters such as mutant KRAS, Epidermal Growth Factor Receptor (EGFR) and integrins to tumor cells with wild-type KRAS." (PMID 41515889, 2025). "Research indicates that EGLN3 inhibits tumor growth by suppressing EGFR signaling, inducing G1-phase cell cycle arrest, and promoting apoptosis." (PMID 41301681, 2025). "On the one hand, it enhances erlotinib-induced autophagy by blocking the interaction between BECN1 and activated epidermal growth factor receptor (EGFR), thereby inhibiting tumor cell growth and survival." (PMID 40723340, 2025). "The utility of anti-PD-1/PD-L1 immunotherapy in EGFR-mutated tumours has been investigated in several trials, which consistently showed that NSCLC tumours with EGFR mutations have a poor response to these therapies." (PMID 40647497, 2025). "For example, patritumab deruxtecan, a HER3-directed ADC, has shown promising efficacy in EGFR-mutated NSCLC, while tusamitamab ravtansine, targeting CEACAM5, has demonstrated anti-tumor activity in preclinical models and early-phase studies." (PMID 41184856, 2025). "It is plausible that in CD2AP-high tumours, the oncogenic activity is partly dependent on a synergistic interplay between EGFR signalling and CD2AP-mediated scaffolding and endocytosis." (PMID 41425578, 2025). "Previous in vitro studies have demonstrated that Gefitinib effectively inhibits EGFR signaling and reduces tumor cell proliferation and macrophage-induced cytokine release." (PMID 41304988, 2025). "In recent studies, Mal-modified PPI G4 dendrimers conjugated to single chain fragment variables were designed to exclusively deliver anti-EGFR siRNA to tumours by receptor-mediated endocytosis." (PMID 40166479, 2025). "By modifying EGFR-mediated anti-angiogenic, antiproliferative, and apoptotic properties, besides macrophage reprogramming, Gefitinib nanoparticles promoted tumor cell death." (PMID 41304988, 2025). "Preblocking BP values were calculated from the plateau, whichrepresented the maximal tumor EGFR available for binding." (PMID 40367338, 2025). "Its mutation can lead to excessive activation of signalling pathways such as EGFR, thereby promoting the growth of tumour cells." (PMID 39833023, 2025).
tumor (continued). "For instance, a single injection of oAd/Cas12a targeting EGFR led to an 88.6% reduction in tumor volume in A549 xenograft mice, highlighting the high efficacy of oAd combined with CRISPR-Cas12a in tumor suppression." (PMID 40968311, 2025). "This study provides novel evidence highlighting EGFR's role in shaping the tumor microenvironment through precise regulatory mechanisms involving miRNA secretion." (PMID 39816681, 2025). "Ourhypothesis for this phenomenon is that receptor competition from excessblocking agents caused EGFR-bound ABY-029 throughout the body (liver,kidney, skin, etc.)to be released back into the blood, increasingmeasured signal in tumor and muscle." (PMID 40367338, 2025). "Although EGFR is considered a classical and important tumor marker, its role in the development of radioresistance is not clear." (PMID 40003899, 2025). "Eliminating EGFR by quinolines effectively blocks the downstream signaling cascades that promote tumor growth and metastasis." (PMID 40074749, 2025). "Results from this phase 2 clinical trial showed that the triple regimen consisting of SMET12, toripalimab and chemotherapy, showed manageable safety and anti-tumor action among advanced NSCLC patients positive for EGFR protein expression." (PMID 41583476, 2025). "Preclinical studies support this rationale: selective CDK4/6 inhibition induced G1 arrest and synergistically reduced tumor cell viability when combined with EGFR blockade in HPV-unrelated HNSCC cell lines." (PMID 41375018, 2025). "For instance, Sorafenib and Erlotinib are multi-target tyrosine kinase inhibitors whose mechanisms of action involve inhibiting signaling pathways such as VEGF and EGFR pathways to block tumor angiogenesis and cell proliferation." (PMID 41179292, 2025). "Concurrently, JHU-083 demonstrated remarkable efficacy in impeding the proliferation of EGFR-driven lung tumors, fostering adaptive T cell-mediated tumor-specific immune responses." (PMID 40598593, 2025). "Here, we comprehensively compared the impact of EGFR overexpression on miRNA profile in both tumor cells and their derived EVs." (PMID 39816681, 2025). "The cleavable linker also confers a bystander effect, allowing payload diffusion to neighboring tumor cells with lower EGFR expression and thereby broadening antitumor activity." (PMID 41375018, 2025). "Overactivation of EGFR can result in rapid tumor cell proliferation and migration, thereby promoting the progression of HNSCC." (PMID 40018039, 2025). "This indicates the effectiveness of CAR-EGFR modification in targeting and killing high-EGFR-expressing tumor cells." (PMID 40002679, 2025). "Higher genetic heterogeneity has been reported in early-stage disease, with selective survival of tumor cells containing key driver mutations (such as KRAS, EGFR variants, etc.)that impart enhanced invasive potentials." (PMID 40282516, 2025). "Our data suggests CMTM4 is a novel regulator of the EGFR/AKT/mTOR pathway in human tumor and affects sensitivity to EGFR tyrosine kinase inhibition." (PMID 39948411, 2025). "Although tumor-targeting peptides like our PD-L1-, EGFR-, and ER-targeting motifs are typically less immunogenic than protein biologics, antibody or T-cell responses can still occur, especially with repeated dosing or modified sequences." (PMID 41304839, 2025). "HDL-C promotes cholesterol accumulation in tumor cell membranes, enhancing epidermal growth factor receptor (EGFR) signaling—an effect more commonly seen in adenocarcinomas in the lower lobes." (PMID 41142602, 2025). "EGFR-positive tumors more frequently exhibited these aggressive histopathological characteristics, supporting EGFR's link tohigh-grade tumor biology." (PMID 41170073, 2025).
tumor (continued). "We retrieved tumor sections from 13 treatment-naive EGFR-mutant NSCLC patients and graded the level of EGFR heterogeneity." (PMID 39747003, 2025). "Mouse anti EGFR clone 31G7,Zymed, Milan, ItalyScored based on intensity and % of tumour positively stained cells (i.e., total score 0–2 as a Low and 3–5 as a high." (PMID 40227788, 2025). "Of 156 patients with RAS&BRAFwt tumours treated with chemotherapy, 44 (28%) received an EGFR-inhibitor in first line, and 68 (44%) in later lines." (PMID 40437037, 2025). "In NSCLC (A549 and H460) cells, UA inhibits the EGFR/JAK2/STAT3 pathway to reduce tumor angiogenesis, migration and invasion, promote apoptosis and induce cell cycle arrest at G0/G1 phase [1063]." (PMID 40490812, 2025). "Another study using paired baseline and re-biopsy samples after progression from EGFR-TKI therapy showed that CD8+ and FoxP3+ tumor-infiltrating lymphocyte densities decreased following EGFR-TKI treatment." (PMID 40002883, 2025). "Fluorescence quantitative result of anti‐EGFR‐coated microplates indicated that N3 group‐labeled exosomes were TExo, implying that N3 group‐labeled TExo spread from tumor tissue to the whole body." (PMID 40498982, 2025). "Previously, in the context of LC, an association of mutations in the EGFR/KRAS genes and an increased expression of VEGFA/VEGFR2 in tumor tissue was demonstrated." (PMID 39940785, 2025). "In this study, we combined analyses of clinical tumor samples and the use of a cell line to evaluate the relationship between CIN and the effect of EGFR-TKIs in EGFR-mutated NSCLC." (PMID 40136696, 2025). "Expression analyses revealed increased EGFR and TF levels with advancing tumor stage, whereas EpCAM expression declined in advanced-stage tumors." (PMID 40806559, 2025). "Elevated EREG expression in the tumor microenvironment, particularly from fibroblasts and macrophages, activates EGFR signaling through autocrine and paracrine loops, enhancing fibroblast migration and contributing to therapeutic resistance in CC." (PMID 40055606, 2025). "Both mechanisms activate the EGFR signaling pathway and synergistically contribute to tumor development." (PMID 39741120, 2025). "In TN BC, the activation of the EGFR pathway often leads to enhanced tumor proliferation and survival, driving the rapid growth that defines this subtype." (PMID 40894036, 2025). "We subsequently evaluated the capacity of bsAbs to impede EGF ligand binding to EGFR expressed on tumor cells." (PMID 41291854, 2025). "In NSCLC, Cluster of Differentiation 200 (CD200)-expressing CAFs have been found to increase tumor cell sensitivity to targeted therapies, such as Epidermal Growth Factor Receptor (EGFR) inhibitors, and this effect disappears when CD200 is absent." (PMID 40940809, 2025). "Research indicates that MIR-34a, by targeting EGFR, can inhibit the growth of lung tumors, and simultaneously regulate the epithelial–mesenchymal transition of tumor cells to suppress tumor metastasis." (PMID 40083325, 2025). "Mutations in KRAS and NRAS lead to continued activation of the epidermal growth factor receptor (EGFR) pathway and promote tumor growth and survival, even with pharmacological blockade of EGFR." (PMID 40698441, 2025). "Knockdown of NT5DC2 in TNBC cells reduces proliferation, migration, invasion, and metabolic activity, while also inhibiting tumor growth and neuropathic pain in mouse models by deactivating the EGFR pathway." (PMID 40109861, 2025). "Numerous active components have been identified from Lingzhi that can inhibit EGFR pathways to suppress tumor growth, induce apoptosis, and block angiogenesis." (PMID 40733125, 2025). "In BC, the abnormal expression of EGFR is related to the invasiveness and prognosis of the tumor, and it is considered an important therapeutic target." (PMID 40819076, 2025).